HSBP1L1 (heat shock factor binding protein 1 like 1)
Synonyms: FLJ10967; MGC189743
Tractability: No criterion of Open Targets' tractability assessment is met for any kind of drug.
Gene: Protein-coding gene on chromosome 18 (79,964,582 to 79,970,823, forward strand). Ensembl gene ENSG00000226742.
Subcellular location (Human Protein Atlas): Nucleoplasm
Gene Ontology:
Molecular function: protein binding; transcription corepressor activity
Biological process: negative regulation of DNA-templated transcription
Genetic constraint (gnomAD): Loss-of-function variants: 3 observed, 1.06 expected, observed/expected ratio (o/e) 2.84. That is too few expected variants to judge how well the gene tolerates losing a copy. Missense variants: 45 observed, 26.52 expected, observed/expected ratio (o/e) 1.7, 90% interval 1.32 to 1.95. Synonymous variants: 19 observed, 12.19 expected, observed/expected ratio (o/e) 1.56, 90% interval 1.06 to 1.93.
Homologues: Orthologues: chimpanzee HSBP1L1 (99% identical), macaque HSBP1L1 (96% identical), pig HSBP1L1 (86% identical), rabbit HSBP1L1 (78% identical), dog HSBP1L1 (77% identical), guinea pig HSBP1L1 (74% identical), rat Hsbp1l1 (74% identical), mouse Hsbp1l1 (70% identical), zebrafish hsbp1l1 (41% identical), Drosophila melanogaster CG5446 (36% identical), Caenorhabditis elegans hsb-1 (24% identical). Paralogues in human: HSBP1 (31% identical).
Diseases named in the same sentence as HSBP1L1 in open-access papers:
HSBP1L1 is named in the same sentence as 2 diseases in open-access papers, as found by Europe PMC text mining. Sharing a sentence is not in itself a finding about the gene and the disease. The quoted sentences say what the papers report.
pancreatic carcinoma (1 paper, 2019). "In conclusion, on the basis of TCGA sequence data, we proposed a four genes model (DNAH10, HSBP1L1, KIAA0513, and MRPL3), which facilitated the discernment of high‐risk patients for worse OS in pancreatic carcinoma." (PMID 31102348, 2019).
HSBP1L1 also shares sentences with these, for which no sentence is quoted: tumor (1 paper).